SOX9 (SRY-box transcription factor 9)
Diseases named in the same sentence as SOX9 in open-access papers (continued):
Sharing a sentence is not in itself a finding about the gene and the disease.
colon carcinoma (continued). "The results showed that the expression of SOX9 and S100P in colon cancer had a high concordance." (PMID 26009899, 2015). "Western blot analysis showed that SOX9 and S100P proteins were both up-regulated in colon cancer." (PMID 26009899, 2015). "Overall, these results were consistent with our hypothesis that SOX9 induction of S100P overexpression in colon cancer cells stimulates cell migration and invasion through activation of the classical EMT signaling pathway." (PMID 26009899, 2015). "Moreover, the linear regression between SOX9 and S100P expression was pronounced in colon cancer TMA analysis." (PMID 26009899, 2015). "In consideration of our previous observation that hsa_circ_0020095 may mediate cisplatin-resistance in colon cancers by modulating the miR-487a-3p/SOX9 axis, this research further supplemented the function of circRNAs in CRC, suggesting a promising target for cancer treatment." (PMID 40495972, 2025). "In line with this hypothesis, we demonstrated that overexpression of SOX9 induces the expression of S100P in both a colon cancer cell line and human samples, leading to increased cell invasiveness and metastasis as well as activation of epithelial-mesenchymal transition (EMT)." (PMID 26009899, 2015). "In colon cancer, PKG also dampens tumorigenesis by inhibiting β‐catenin/TCF and SOX9 signaling, thereby reducing angiogenesis and proliferation." (PMID 40304310, 2025). "DKK2 expression in colon cancer promotes LYZ+ cancer cell generation through the regulation of HNF4α1, which suppresses expression of Sox9, the transcription factor for Paneth cell differentiation." (PMID 38659853, 2024). "To demonstrate that S100P is induced as a result of SOX9 overexpression in colon cancer, we performed EMSA and quantitative ChIP assays, and we found that SOX9 protein binds to the potential binding site in the S100P promoter (AAACAAAAG)." (PMID 26009899, 2015). "As we previously reported, HMGA1 and SOX9 are upregulated in colon cancer compared with nonmalignant epithelium." (PMID 39895630, 2025). "Moreover, PAF1 knockdown decreased the expression levels of the genes such as LGR5, ID1, ID3, CD44v9, CD133, BMI1, RNF43, EPHB2, SOX9, and ASCL2, which are critical for inducing colon cancer stemness and its markers." (PMID 38182897, 2024). "HMGA1 is also highly up-regulated in colon cancer compared with nonmalignant epithelium, and SOX9 becomes overexpressed during colon carcinogenesis." (PMID 35328637, 2022). "Furthermore, in colon carcinoma cells, an active β-catenin-TCF4 complex is required for physiological targeting of SOX9." (PMID 28279198, 2017). "Furthermore, SOX9 regulates E-cadherin, N-cadherin, vimentin and Snail expressions at protein and mRNA levels, mediates EMT, promotes colon cancer metastasis." (PMID 26755651, 2016). "To explore the clinical relevance of SOX9 regulation of S100P expression in colon cancer, we performed IHC analysis of the tissue microarray (TMA) containing 90 pathologically annotated cases of colon cancer." (PMID 26009899, 2015). "The functional effect of SOX9 knockdown on cell behavior in colon cancer cell lines in vitro was assessed by transfecting SOX9 siRNA lentivirus into HCT116 cells to generate stable transfectants (HCT116-SOX9(−))." (PMID 26009899, 2015). "In order to validate the implication of SOX9 and/or SOX10 factors in meloe promoter activation, we co-transfected expression vectors coding these factors, together with the P-644 plasmid in a colon carcinoma cell line (SW480) and a mesothelioma cell line (Meso163)." (PMID 24086527, 2013). "The upreguation of TAGLN and downregulation of SOX9, IRS1, P15, AREG, IER5L, KRT8 in RKO, SW620 and CW2 colon cancer cells indicated these genes may be the target molecules for the biological behaviour of IGFBP-rP1 in colon cancer." (PMID 20977730, 2010).
colon carcinoma (continued). "We found that IGFBP-rP1 could upreguate TAGLN, downregulate SOX9, IRS1, P15, AREG, IER5L, KRT8 in these colon cancer cells, indicating that these genes may be the important IGFBP-rP1 responsible genes in colon cancer." (PMID 20977730, 2010). "Downregulation of IRS1 and SOX9 by both IGFBP-rP1 and sodium butyrate in colon cancer cells indicated that these two genes may play important roles in the differentiation and apoptosis induction process in colon epithelium." (PMID 20977730, 2010). "In colon cancers, KLF4 could be down-regulated by caudal type homeobox 2 (CDX2), notch signaling, transcription factor 4 (TCF4) or sex determining region Y-box 9 (Sox9)." (PMID 22937066, 2012).
pancreatic cancer (44 papers, 2015 to 2026). "Our data demonstrate ambiguous impact of SOX9 suppression on the expression of genes associated with antitumor drug resistance in pancreatic cancer cells." (PMID 40141294, 2025). "To further test this idea, we lentivirally transduced a construct encoding BMI1 gene in MKN45 GC cells and Panc-1 and RWP-1 pancreatic cancer cells with SOX9 knockdown or controls." (PMID 31941916, 2020). "Mechanistically, pharmacological inhibition with fatostatin and genetic SREBP knockdown suppresses tumor growth through the downregulation of SRY-box transcription factor 9 (SOX9), a key marker in early pancreatic neoplasm development." (PMID 41550359, 2026). "In particular, pancreatic cancer cells with high levels of SOX9 exhibit increased resistance to gemcitabine in comparison to cells with low levels of this protein." (PMID 40141294, 2025). "SOX9 overexpression has been observed in multiple tumor types, including pancreatic cancer, and is discussed as a prognostic marker." (PMID 40141294, 2025). "It should be emphasized that the effect of SOX9 on proliferation differs in different pancreatic cancer cells and in different tumors." (PMID 40141294, 2025). "Earlier we discovered that the down-regulation of SOX9 expression in the pancreatic cancer cell lines leads to cell line-specific changes in expression levels of epithelial and mesenchymal protein markers." (PMID 40141294, 2025). "The knockdown of MMP1 in pancreatic cancer cell lines decreased the expression of ductal markers such as SOX9 while the overexpression of MMP1 in hTERT-HPNE increased the expression of ductal markers, suggesting its function of maintaining ductal identity." (PMID 40092486, 2025). "To this end, we have conducted a full-transcriptome analysis of pancreatic cancer cell lines under SOX9 knockdown." (PMID 40141294, 2025). "The expression levels of genes comprising prognostic signatures for pancreatic cancer were also evaluated following SOX9 knockdown." (PMID 40141294, 2025). "In order to gain a more profound understanding of the role of SOX9 in pancreatic cancer, we have performed SOX9 knockdown in the COLO357 and PANC-1 cells using RNA interference, followed by full-transcriptome analysis of the siRNA-transfected cells." (PMID 40141294, 2025). "In the context of pancreatic cancer cells, the inhibition of SOX9 has been shown to induce cell-line-specific effects on proliferative activity, expression of EMT markers, and activation of apoptotic caspases." (PMID 40141294, 2025). "Since the substrate sets of ABCA1-2, ABCB1, ABCC5, and ABCG2 overlap, the general effect of SOX9 suppression on overall or partial drug resistance of pancreatic cancer cells in context of these ABC proteins cannot be predicted with certainty." (PMID 40141294, 2025). "Analyzing effects of SOX9 knockdown on immunity-related genes in pancreatic cancer cells, we received somewhat contradictory results their estimates depending on statistical tests used." (PMID 40141294, 2025). "Additional studies are needed to assess the properties and prognostic significance of SOX9 in pancreatic cancer using other biological models." (PMID 40141294, 2025). "MYEOV can enhance the DNA-binding activity of SOX9 in pancreatic cancer tissue, thereby promoting the progression of pancreatic cancer." (PMID 40535130, 2025). "Specifically, SOX9 has been found to influence self-renewal, invasion, and proliferation in lung, hepatocellular, breast, prostate, skin, and pancreatic cancers." (PMID 41031891, 2025).
pancreatic cancer (continued). "In all the investigated pancreatic cancer cell lines, the downregulation of SOX9 led to an increase in the levels of the cell cycle inhibitor protein (CDKN1A)." (PMID 35884771, 2022). "Considering the natural heterogeneity of pancreatic cancer cells, we analyzed the cell response to the downregulation of SOX9 in six different cell lines." (PMID 35884771, 2022). "In our work, we also showed that the overexpression of SOX9 in two pancreatic cancer cell lines, BxPC-3 and Colo357, results in increased cell proliferative activity and decreased CDKN1A expression levels." (PMID 35884771, 2022). "Second, we conclude that cell response to SOX9 expression downregulation depends on the cell line and is apparently defined by the genomic and epigenomic changes in pancreatic cancer cells, which were acquired during carcinogenesis." (PMID 35884771, 2022). "We chose the method of downregulation of SOX9 expression via siRNA transfection as the main method for investigating the functional role of the SOX9 factor in pancreatic cancer cells." (PMID 35884771, 2022). "The acquired results demonstrate that the SOX9 protein exerts its multiple functions as a regulator of differentiation and a potential promoter of tumor growth in a cell-specific manner in pancreatic cancer cells." (PMID 35884771, 2022). "Altogether, these results confirm that SOX9 sustains the self-renewal and tumor initiation activity in pancreatic cancer." (PMID 35205666, 2022). "SOX9 is required for maintaining the pancreatic ductal identity and it is involved in the initiation of pancreatic cancer." (PMID 35205666, 2022). "As cancer cell motility and invasion into the basement membrane are associated with the induction of EMT and metastasis, we investigated these capabilities in pancreatic cancer cells overexpressing SOX9." (PMID 35205666, 2022). "In our experiments, the GATA4 factor demonstrated a decrease in the expression in three out of six pancreatic cancer cell lines (Colo357, MiaPaCa-2, and Panc1) with the downregulated expression of SOX9." (PMID 35884771, 2022). "In our study, we discovered a link between the expression of SOX9 in pancreatic cancer cell lines and the expression of the GATA4 and GATA6 proteins." (PMID 35884771, 2022). "Altogether, these observations establish that high levels of SOX9 in pancreatic cancer cells facilitate their acquisition of the cellular and molecular traits required for the metastatic dissemination and colonization." (PMID 35205666, 2022). "For instance, MYEOV upregulation is linked with undesirable survival outcome of pancreatic cancer, which elevates the HES1 expression and triggers pancreatic cancer progression through enhancing SOX9 trans-activity." (PMID 35662734, 2022). "SOX9 can also maintain pancreatic progenitor cells by stimulating the proliferation, survival and persistence of pancreatic cancer cells." (PMID 34935260, 2022). "For the purpose of studying the effect of the SOX9 protein expression on the pancreatic tumor phenotype, we chose to downregulate the SOX9 expression via synthetic siRNA targeting SOX9 RNA." (PMID 35884771, 2022). "siSOX9 transfection effectively downregulated the expression of SOX9 in all the investigated pancreatic cancer cell lines." (PMID 35884771, 2022). "Altogether, our findings highlight the relevance of SOX9 in pancreatic cancer outcomes due to its role in metastasis and to recurrence after therapy." (PMID 35205666, 2022). "Mechanistically, we have identified stem cell factors rather than EMT factors as important mediators of the oncogenic activity of SOX9 in pancreatic cancer." (PMID 35205666, 2022). "Supporting this idea, their expression correlated negatively with SOX9 expression in human pancreatic cancer samples from the TCGA cohort." (PMID 35205666, 2022).
pancreatic cancer (continued). "For instance, in pancreatic tumors, the expression of SOX9 positively correlates with the expression of epithelial phenotype genes (CDH1, KRT7, KRT18, and KRT19) and negatively correlates with the expression of the mesenchymal phenotype gene VIM." (PMID 35884771, 2022). "Considering these data, the results we acquired also suggest that in pancreatic cancer cells, SOX9 is a negative regulator of CDKN1A activity." (PMID 35884771, 2022). "MYEOV promotes pancreatic cancer progression by enhancing transactivity of SOX9, a tumorigenic gene of pancreatic cancer." (PMID 34659542, 2021). "As a result, ductal (CA2, CK19, and SOX9)/pancreatic cancer (EpCAM and CD44) markers decreased and acinar markers (SYP and PTF1A) increased by inhibitor treatment in KiPCs." (PMID 33233448, 2020). "This indicates that the expression of Sox9 plays an important role in chemoresistance by the induction of stemness in pancreatic cancer cells." (PMID 31057614, 2019). "Our studies show clearly that the SOX9 positive populations in foregut development and regeneration and pancreatic cancer are heterogeneous." (PMID 30814526, 2019). "Studies in murine pancreatic cancer show that SOX9 reprograms acinar cells to ductal cells during carcinogenesis." (PMID 28452345, 2017). "In keeping with this finding, NF-κB positively regulates expression of the pancreatic progenitor marker, SOX9, in human pancreatic cancer stem cells." (PMID 26218223, 2015). "The transcription factor SOX9 was recently shown to be increased in L3.6pl independently of the presence of hypoxic or normoxic conditions and to have pancreatic tumor-promoting effects." (PMID 25650658, 2015). "SOX9 was identified as a transcription factor that regulates hypoxia-related, pancreatic cancer-aggravating genes independently of hypoxia." (PMID 25650658, 2015). "SOX9 gene expression is known to be altered during the development of pancreatic tumors." (PMID 40141294, 2025). "These are additional indications of tumor-suppressive ability of SOX9 in pancreatic cancer." (PMID 40141294, 2025). "Alterations of the expression of transcription factors, epithelial–mesenchymal transition markers, oncogenes, tumor suppressor genes, and drug resistance-related genes upon SOX9 knockdown in comparison of primary and metastatic pancreatic cancer cells are discovered." (PMID 40141294, 2025). "Consequently, SOX9 is regarded as a prognostic marker of pancreatic cancer progression and treatment." (PMID 40141294, 2025). "SOX9 is one of the most important genes up-regulated during early tumor formation in breast, lung cancer, hepatocarcinoma cells, esophageal squamous cell carcinoma cells, osteosarcoma, and pancreatic cancer." (PMID 40141294, 2025). "Furthermore, ST6GAL1 upregulation in ovarian and pancreatic carcinomas induces the expression of SRY-box transcription factor 9 (SOX-9) and Snail family transcriptional repressor 2 (SNAI2), both key tumor-promoting transcription factors." (PMID 39937175, 2025). "Importantly, through both gain- and loss-of-function approaches, we functionally demonstrated that SOX9 promotes the migration and invasion of pancreatic cancer cells and facilitates the metastatic dissemination and colonization of distant organs in vivo." (PMID 35205666, 2022). "Therefore, our results demonstrate that the suppression of SOX9 expression in pancreatic cancer cells leads to specific changes in the expression profiles of development regulatory proteins." (PMID 35884771, 2022). "Prior to studying the effects of SOX9 on differentiation and cell growth in pancreatic cancer, we investigated the expression level of the SOX9 protein in several well-characterized pancreatic cancer cell lines, AsPC-1, BxPC-3, Colo357, Capan-2, MiaPaCa-2, and Panc1." (PMID 35884771, 2022). "Some evidence indicates that high SOX9 may promote pancreatic cancer cell invasion and aggressiveness, as well as chemoresistance, while others have reported low levels of SOX9 expression." (PMID 35205666, 2022).